PRDX1 (peroxiredoxin 1)
Description:
Thiol-specific peroxidase that catalyzes the reduction of hydrogen peroxide and organic hydroperoxides to water and alcohols, respectively. Plays a role in cell protection against oxidative stress by detoxifying peroxides and as sensor of hydrogen peroxide-mediated signaling events. Might participate in the signaling cascades of growth factors and tumor necrosis factor-alpha by regulating the intracellular concentrations of H(2)O(2). Reduces an intramolecular disulfide bond in GDPD5 that gates the ability to GDPD5 to drive postmitotic motor neuron differentiation (By similarity).
Synonyms: NKEF-A; PAG; PAGA; PAGB; TDPX2; NKEFA; MSP23; PRX1; PRXI
Tractability: Small molecule: a structure with a bound ligand is known; a high-quality ligand is known; it has a binding pocket of medium quality. PROTAC: UniProt records ubiquitination sites on it; ubiquitination databases record sites on it; its protein half-life has been measured; a small molecule that binds it is known.
Target class: Enzyme; Oxidoreductase
Gene: Protein-coding gene on chromosome 1 (45,510,914 to 45,542,816, reverse strand). Ensembl gene ENSG00000117450.
Subcellular location: Cytoplasm; Melanosome
Subcellular location (Human Protein Atlas): Mitochondria
Pathways (Reactome):
Cellular responses to stimuli: Detoxification of Reactive Oxygen Species; NFE2L2 regulating anti-oxidant/detoxification enzymes
Disease: Deregulated CDK5 triggers multiple neurodegenerative pathways in Alzheimer's disease models
Vesicle-mediated transport: Scavenging by Class B Receptors
Gene Ontology:
Molecular function: cadherin binding; peroxidase activity; protein binding; RNA binding; thioredoxin peroxidase activity; thioredoxin-dependent peroxiredoxin activity; antioxidant activity; identical protein binding; oxidoreductase activity; peroxiredoxin activity
Biological process: hydrogen peroxide catabolic process; natural killer cell activation; cell population proliferation; leukocyte activation; removal of superoxide radicals; response to oxidative stress; skeletal system development
Cellular component: cytoplasm; extracellular exosome; extracellular region; nucleus; cytosol; melanosome
Genetic constraint (gnomAD): Loss-of-function variants: 19 observed, 21.08 expected, observed/expected ratio (o/e) 0.9, 90% interval 0.63 to 1.32. The upper end of that interval is the gene's LOEUF score, 1.32, which puts it in group 5 of 6, group 1 being the genes least tolerant of losing a copy. Missense variants: 226 observed, 248.48 expected, observed/expected ratio (o/e) 0.91, 90% interval 0.81 to 1.02. Synonymous variants: 89 observed, 85.52 expected, observed/expected ratio (o/e) 1.04, 90% interval 0.88 to 1.24.
Homologues: Orthologues: chimpanzee PRDX1 (100% identical), macaque PRDX1 (99% identical), guinea pig PRDX1 (99% identical), rat Prdx1 (97% identical), pig PRDX1 (97% identical), rat Prdx1l1 (97% identical), mouse Prdx1 (95% identical), dog PRDX1 (88% identical), zebrafish prdx1 (81% identical), tropical clawed frog prdx1 (76% identical), Drosophila melanogaster CG12896 (32% identical), Drosophila melanogaster Prx6b (32% identical), and 1 more. Paralogues in human: PRDX2 (77% identical), PRDX4 (70% identical), PRDX3 (62% identical), PRDX6 (33% identical).
Diseases named in the same sentence as PRDX1 in open-access papers:
PRDX1 is named in the same sentence as 206 diseases in open-access papers, as found by Europe PMC text mining. Sharing a sentence is not in itself a finding about the gene and the disease. The quoted sentences say what the papers report.
breast cancer (46 papers, 2007 to 2025). A primary or metastatic malignant neoplasm involving the breast. "Low PRDX1 protein and mRNA expression have been linked to improved survival and better prognosis in gastric cancer, breast cancer, and hepatocellular carcinoma, which was previously attributed only to the role of PRDX1 in redox signaling." (PMID 40387816, 2025). "High mRNA expression of PRDX1/2/4/5/6 was significantly associated with shorter relapse-free survival in breast cancer patients." (PMID 36835577, 2023). "The co-immunoprecipitation assay showed that Prdx1 downregulation led to dissociation of the Prdx1-GSTπ-JNK1 complex in HBXIP/Nrf2 feedback loop-deficient breast cancer cells." (PMID 35027562, 2022). "Studies also indicated that PRDX1 interacts with the c-Myc oncogene and can inhibit its transcriptional activity and high expression of PRDX1 appears to be associated with less aggressive breast cancers." (PMID 25632391, 2015). "After initially screening a large cohort of breast cancer patients to assess the prognostic potential of PRDX1, we observed that in the ER-positive subset of tumors, high PRDX1 protein expression was associated with improved survival." (PMID 25011585, 2014). "The aim of this study was to elucidate the association between PRDX1 protein levels and survival in two independent breast cancer cohorts, using two orthologous methods of assessing protein expression levels, namely RPPA and TMA technology." (PMID 25011585, 2014). "Accordingly, a recent study suggests that high PRDX1 expression appears to be associated with less aggressive breast cancers." (PMID 25011585, 2014). "Prdx1-deficient mice suffer from shortened survival due to development of hemolytic anemia and multiple tumors, including mammary carcinomas." (PMID 25011585, 2014). "The goal of this study was to investigate the role of miR-510 in breast cancer cell migration and tumor growth and to verify PRDX1 as the direct miR-510 target underlying the mechanism of these phenotypic changes." (PMID 23971998, 2013). "Through its antioxidant function, PRDX1 may prevent oxidative stress-mediated ERα loss, thereby potentially contributing to maintenance of an ER-positive phenotype in mammary tumors." (PMID 25011585, 2014). "However, other studies have shown that overexpression of PRDX1 mRNA in human breast carcinoma is associated with higher tumor grade, and high expression of cytoplasmic PRDX1 protein correlated with increased risk of local recurrence after radiotherapy." (PMID 25011585, 2014). "For one thing, PRDX1 may prevent oxidative stress-mediated ERα loss through antioxidant function, thereby contributing to maintaining the ER-positive phenotype of breast tumors and improving the prognosis of breast cancer." (PMID 34490047, 2021). "Indeed, while genetic knock-outs of other peroxiredoxins do not significantly hamper the survival of the animals and cause relatively mild defects, Prdx1-deficient mice suffer from shortened survival due to development of hemolytic anemia and multiple tumors, including mammary carcinomas." (PMID 32316111, 2020). "The expressionof PRDX1 in breast cancer was evaluated using TCGA data, which revealedthat PRDX1 is highly expressed in breast cancer and localized in thecytoplasm." (PMID 40028362, 2025). "For example, PRDX1 participates in the signaling pathway of fibroblast proliferation, which serves as a bio-marker to characterize progression and metastasis of human breast cancer." (PMID 38783355, 2024). "Normal levels of PRDX1 have been shown to protect several proteins from oxidative damage, such as the oestrogen receptor, and serve as a factor for favourable prognosis of breast cancers and preventing ROS-induced senescence via p38MAPK." (PMID 38067110, 2023). "Overexpression and the oncogenic function of PRDX1 were demonstrated in many cancers, including breast cancer, non-small-cell lung carcinoma, pancreatic ductal adenocarcinoma (PDAC), and colorectal cancer." (PMID 37031183, 2023).
breast cancer (continued). "Many studies have revealed that PRDX1-regulated ROS-dependent signaling pathways play a key role in the development of various cancers, including breast cancer, esophageal cancer, lung cancer, prostate cancer, and pancreatic cancer." (PMID 37198696, 2023). "The expression status of HBXIP and Prdx1 in 128 breast cancer tissues was determined using immunohistochemical (IHC) staining." (PMID 35027562, 2022). "For example, SIRT2 can inhibit the antioxidant activity of peroxiredoxin-1 (Prdx-1), rendering breast cancer cells sensitive to ROS-induced DNA damage and cytotoxicity, leading to apoptosis in breast cancer cells." (PMID 36101744, 2022). "Rescued overexpression of Prdx1 decreased the apoptosis rate of HBXIP/Nrf2 doubles KD breast cancer cells following ECM detachment." (PMID 35027562, 2022). "This pattern indicates that Prdx1 accumulation mediated by HBXIP contributes to breast cancer development." (PMID 35027562, 2022). "A markedly positive correlation was observed between HBXIP expression and Prdx1 expression in 994 patients with breast cancer." (PMID 35027562, 2022). "This pattern suggests that Prdx1-mediated JNK1 activation is involved in HBXIP/Nrf2 feedback loop-induced anoikis resistance in addition to diminishing ROS levels in breast cancer cells." (PMID 35027562, 2022). "On the other hand, SIRT2 can reduce the activity of peroxiredoxin-1 (Prdx-1) through deacetylation which leads to breast cancer cells accumulating reactive oxygen species (ROS) and becoming less viable." (PMID 34368168, 2021). "For example, recent studies have shown that the role of peroxidase 1 (PRDX1) as an antioxidant in breast cancer has two sides." (PMID 34490047, 2021). "Simultaneously, however, PRDX1 can protect breast cancer cells from the effects of certain forms of treatment, including prooxidant compounds, and therefore can be regarded an attractive target for anticancer therapies in mammary malignancies." (PMID 32316111, 2020). "In a breast cancer rodent model, CPA and DOX caused increased expression of oxidative stress related genes such as glutathione peroxidase 1 (GPX1), peroxiredoxin 1 (PRDX1), and NF-ΚB in the hippocampus." (PMID 33352780, 2020). "We would like to point out the “paradoxical dualism” of PRDX1 expression and its role in breast cancer, including TNBC." (PMID 32316111, 2020). "Recent studies have shown that PRDX1 functioning as a potential oncogene was observed in numerous cancers, including ovarian cancer, head and neck squamous cell carcinoma, and breast cancer." (PMID 32382548, 2020). "Another study also revealed that higher mRNA expression of PRDX1/2/4/5/6 was correlated with worse prognosis, while high levels of PRDX3 were associated with favorable prognosis of patients with breast cancer." (PMID 32908916, 2020). "In our previous studies, we showed that the downregulation of PRDX1 in breast cancer cell lines, including TNBC cell lines, results in markedly increased toxicity of Asc." (PMID 32316111, 2020). "As PRDX1 was reported to be upregulated in breast cancer in general, we hereby analyzed the publicly available dataset for the gene expression of PRDX1 mRNA within the TNBC subtype as compared to non-malignant tissues." (PMID 32316111, 2020). "Generally, the idea of targeting PRDX1 in breast cancer has been proposed previously, and that notion originates from the observation that PRDX1 can inhibit H2O2-induced cell death in mammary carcinoma cells." (PMID 32316111, 2020). "Conversely, peroxiredoxin-1 (PRDX1) downmodulation was shown to be beneficial for breast cancer therapy, especially in concomitance with prooxidant agents." (PMID 31627322, 2019). "Our study pinpoints the dominant role for PRDX1 in management of exogeneous oxidative stress by breast cancer cells and substantiates further exploration of PRDX1 as a target in this disease, especially when combined with prooxidant agents." (PMID 30287919, 2018).
breast cancer (continued). "On the contrary, PRDX1 has a tumor promoting role in breast cancer, bladder cancer, oral squamous cell carcinoma, lung cancer, and esophageal squamous cell carcinoma through activation of NF-κB pathway, FOXO1-mediated pathway, and mTOR/p70S6K pathway." (PMID 30104402, 2018). "To conclude, in the current study we have shown that PRDX1 is an essential enzyme in managing the H2O2-mediated oxidative stress in breast cancer cells in vitro and in vivo." (PMID 30287919, 2018). "We seek to validate the dependence of mammary tumour cell survival on an increased expression of PRDX1 or PRDX2 within the current study." (PMID 30287919, 2018). "The question shall be addressed how PRDX1 can be specifically targeted in breast cancer cells in a living organism." (PMID 30287919, 2018). "Identifying PRDX1 as a dominant antioxidant enzyme in breast cancer cells can have significant implications for understanding the biology and pathophysiology of this disease and future design of prooxidant therapies in mammary malignancies." (PMID 30287919, 2018). "From these cumulative observations, we conclude that PRDX1 plays in breast cancer a role somewhat similar to oestrogen receptor—i.e., of a “lesser evil”." (PMID 30287919, 2018). "This corroborates the notion of PRDX1 acting as a “shield” for other 2-Cys PRDXs, and indicates one of the potential explanatory mechanisms for the particular role for PRDX1 in protection of breast cancer cells against oxidative stress." (PMID 30287919, 2018). "Altogether, these results suggest the universality of the effects of PRDX1 targeting among various molecular types of mammary carcinomas." (PMID 30287919, 2018). "While PRDX3, PRDX4, and PRDX6 play a tumor-promoting role in the progression of many cancers, PRDX5, similar to PRDX1, has an antitumor effect in breast cancer development." (PMID 27418953, 2016). "In fact, PRDX1 interacts with the c-Myc oncogene and suppresses its transcriptional activity playing a tumor-suppressive role in breast cancer development." (PMID 27418953, 2016). "Inhibition of PRDX1/2 antioxidant activity with adenanthin dramatically reduced ERα levels in breast cancer cells." (PMID 25011585, 2014). "Although H2O2 induced a decrease of E-cadherin protein expression in breast cancer cells, these changes were only minimally affected by changes in PRDX1 expression." (PMID 25011585, 2014). "As PRDX1 is a natural antioxidant enzyme, we were interested in further elucidating the links between PRDX1, ROS and regulation of ERα levels in breast cancer." (PMID 25011585, 2014). "In the present study, four PRDX members (PRDX1, 2, 4 and 6) were identified to exhibit upregulated levels of expression in the breast cancer tissues." (PMID 24932247, 2014). "This is the first report showing a functional connection between expression of PRDX1 and ERα in breast cancer." (PMID 25011585, 2014). "Using a comprehensive antibody-based proteomics approach, we interrogated PRDX1 protein as a putative biomarker in estrogen receptor (ER)-positive breast cancer." (PMID 25011585, 2014). "Herein, we demonstrate a robust approach for interrogating the role of PRDX1 as a putative protein biomarker in breast cancer." (PMID 25011585, 2014). "PRDX1 protein expression was evaluated in two independent breast cancer cohorts, represented on a screening RPPA (n = 712) and a validation tissue microarray (n = 498)." (PMID 25011585, 2014). "Another proposed function for PRDX1 in breast cancer is as a sensor in H2O2-mediated stress-induced senescence." (PMID 25011585, 2014). "Although differential PRDX1 expression has been described in many tumors, the potential role of PRDX1 in breast cancer remains highly ambiguous." (PMID 25011585, 2014). "An anti-PRDX1 antibody was validated in breast cancer cell lines using immunoblotting, immunohistochemistry and reverse phase protein array (RPPA) technology." (PMID 25011585, 2014).
breast cancer (continued). "We show that miR-510 directly binds to the 3'UTR of PRDX1 and blocks its protein expression, thereby suppressing migration of human breast cancer cells." (PMID 23971998, 2013). "Another study demonstrated that PRDX1 knockdown results in oxidative stress-induced suppression of ERα in T-47D and ZR-75-1 breast cancer cells and sensitizes MCF-7, ZR-75-1, T-47D, MDA-MB-231, HCC-1806, and SK-BR-3 breast cancer cells to the cytotoxic effects of oxidative stress-inducing agents." (PMID 40214422, 2025). "Among the PRDX isoforms, PRDX1 and PRDX2 have been identified in EVs associated with breast cancer." (PMID 40214422, 2025). "Moreover, it has been shown that targeting PRDX1 sensitizes breast cancer cells to pro‐oxidative agents." (PMID 37259925, 2023). "Furthermore, a strong positive correlation was identified between HBXIP expression and Prdx1 expression in clinical breast cancer tissues and TCGA Pan-Cancer Atlas clinical data of breast invasive carcinoma based on the cBioPortal cancer genomics database." (PMID 35027562, 2022). "Co-expression of HBXIP and Prdx1 predicts a poor prognosis for breast cancer patients." (PMID 35027562, 2022). "However, peroxiredoxin-1 is also reported to act as a tumor suppressor in some cancers, especially in breast cancers." (PMID 35454982, 2022). "Because the cellular Prdx1 protein level is also affected by HBXIP in addition to Nrf2 in breast cancer cells, we tested whether these two proteins are correlated in clinical breast cancer tissues." (PMID 35027562, 2022). "Moreover, in ECM-detached Nrf2 knockdown breast cancer cells, the Prdx1 level was positively correlated with the HBXIP level, but the ubiquitinated Prdx1 level showed the opposite trend." (PMID 35027562, 2022). "In addition, correspondingly to our previous results in other subtypes of breast cancer, knockdown of PRDX1 results in inhibition of growth, as assessed in a colony formation assay, and an increase of oxidative stress in MDA-MB-231 TNBC model cell line." (PMID 32316111, 2020). "The role of PRDX1 during the development of breast cancer is, however, complex." (PMID 32316111, 2020). "The up-regulation of PRDX1 has been observed in bladder cancer, breast cancer, colorectal cancer, lung cancer, gastric cancer, liver cancer, pancreatic cancer, sarcoma, leukemia and lymphoma, while down-regulation was detected in esophageal, head and neck cancers and myeloma." (PMID 32455559, 2020). "In breast cancer, over-expression of PRDX1 14, 15, PRDX2 16, PRDX3 17, and PRDX6 18 was shown." (PMID 32231717, 2020). "Similarly, in breast cancer 66, low nuclear but high cytoplasmic PRDX1 expression was also demonstrated." (PMID 32231717, 2020). "In summary, we demonstrate for the first time that JNK is regulated by PRDX1 in the transition of activated fibroblasts into CAFs and therefore may be a new potential drug target in stroma rich cancers such as breast cancer." (PMID 31419957, 2019). "PRDX1 is an antioxidant enzyme, but its role in breast cancer is controversial." (PMID 31686989, 2019). "This suggests that an abrupt inhibition of PRDX1 in breast cancer could be a potential therapeutic modality in this disease, especially when combined with prooxidant therapies." (PMID 30287919, 2018). "Previous studies have shown that PRDX1 might play tumor suppressive role in breast cancers, and the anti-tumor effect of PRDX1 was regulated via c-Myc or PTEN pathways." (PMID 30104402, 2018). "Similar to breast cancer, the functions of PRDX1 in oesophageal cancer remain enigmatic." (PMID 27653015, 2017). "It was also found that drug resistance formation is accompanied by a significant increase in the expression of PRDX1 gene in breast cancer cell strains, which confirms the important contribution of redox‐dependent mechanisms to the development of cisplatin resistance of cancer cells." (PMID 27653015, 2017). "Conversely, there are several reports indicated that PRDX1 may act as a tumour suppressor in breast cancer." (PMID 27653015, 2017).